CD163 (CD163 molecule)
Diseases named in the same sentence as CD163 in open-access papers (continued):
Sharing a sentence is not in itself a finding about the gene and the disease.
Sepsis (continued). "The monocyte/macrophage surface expression of both CD163 and CD206 are increased in sepsis, and are regarded markers of monocyte/macrophage activation." (PMID 24637679, 2014). "The data from the present study showthat CD64 and CD163 expressions on neutrophils and monocytes are elevated incritically ill neonates and children with SIRS with sepsis." (PMID 18604302, 2008). "This multidimensional regulatory network may initially present a pro-inflammatory state (dominated by CD27/RETN) in early sepsis, transitioning to immunosuppression (upregulation of KLRB1/CD163) in later stages." (PMID 41472734, 2025). "Further survival analysis revealed that while the expression levels of KLRB1, RETN, and CD163 significantly influenced sepsis prognosis, CD27 did not demonstrate statistical significance." (PMID 41472734, 2025). "sCD163, the soluble situation of CD163, has been confirmed and can be used as a biomarker for early diagnosis of severe infection and sepsis in adults, and is one of the reference indicators for judging the immune status of children with sepsis." (PMID 40626122, 2024). "Furthermore, we labeled M1-LIKE (CD80+) and M2-LIKE (CD163+) and the data indicated that M2-LIKE cells were significantly higher than M1-LIKE cells in the peripheral blood of sepsis patients." (PMID 36845133, 2023). "While soluble CD163 is not a feature of either the HScore or HLH-2004 criteria, its value as a diagnostic and prognostic biomarker in sepsis-associated HLH has been demonstrated in a different patient population." (PMID 33803997, 2021). "CD163 has also been shown to be elevated in SIRS and sepsis in adults." (PMID 32292492, 2020). "In accordance with the human data, we observed that mice with induced sepsis by injection of a non-lethal dose of Listeria monocytogenes experienced a high and long-term increase in exosome CD163 with peak values 7 days after infection." (PMID 28084321, 2017). "The present work demonstrates that serum concentrations of the macrophage-related proteins sMR, sCD163 and monocyte-bound CD163 expression are higher in patients with severe sepsis or septic shock compared with critically ill non-septic patients." (PMID 24637679, 2014). "The increased expression of CD163 and CD206 indicates that monocytes may acquire the AAM phenotype during sepsis." (PMID 22693573, 2012). "It was shown that the CD163 mean fluorescence intensity for neutrophils and monocytes and the CD163 index for neutrophils could be used to discriminate between SIRS and sepsis in this population." (PMID 22693573, 2012). "In this study, we have shown thatexpression of CD64 and CD163 on neutrophils and monocytes is elevated inpatients with sepsis compared with patients with noninfectious SIRS." (PMID 18604302, 2008). "Therefore, CD64 MFI, CD163 MFI, CD64indexes for neutrophils and monocytes and CD163 index for neutrophils can all beused for discrimination of SIRS and sepsis in critically ill neonates andchildren." (PMID 18604302, 2008). "Soluble CD163 hasbeen found to be elevated in sepsis in adults, whereas surfaceexpression of membrane CD163 (mCD163) in sepsis has not yet been evaluated." (PMID 18604302, 2008). "The first aim of the study was to evaluate the expressionof CD64 and CD163 on neutrophils and monocytes in critically ill neonates andchildren with SIRS and sepsis and to find out whether it can discriminatebetween infectious and noninfectious SIRS." (PMID 18604302, 2008). "Also, hemolysis, a non-exceptional process in severe sepsis/septic shock, influences the expression of the CD163, the scavenger receptor of hemoglobin." (PMID 28380034, 2017). "In an in vitro model of sepsis-related ARDS, co-culture with transgene-inactive and transgene-active HSD-1 tMSCs had no impact on AM surface expression of C206, CD163, CD80, SIRPα or Mer." (PMID 39036559, 2024).
Sepsis (continued). "Non-diabetic sepsis patients further presented with decreased CD33 and up-regulated CD163 expression density, which was absent in diabetic patients." (PMID 36687421, 2022). "The expression of CD163 on both monocytes and neutrophils was higherin septic patients than in patients with noninfectious SIRS both at the time ofsuspected sepsis and 24 hours later." (PMID 18604302, 2008).
ovarian carcinoma (78 papers, 2013 to 2026). A malignant neoplasm originating from the surface ovarian epithelium. "While CD163 is typically regarded as a marker of M2 polarization, which is linked to anti-inflammatory and tissue repair functions, its role in ovarian cancer is more complex." (PMID 40330466, 2025). "The expression level of CD163+ in malignant lesions is significantly higher than that in benign lesions, which is strongly associated with poor prognosis for ovarian cancer." (PMID 39337506, 2024). "Recent studies reported that CD163+ TAMs were associated with PD-L1 expression on tumor cells in several human cancers, including gastric adenocarcinoma, ovarian cancer, NSCLC, and so forth." (PMID 38189834, 2024). "It was recently reported that CD47 expression is upregulated in ovarian cancer cells and associated with poor prognosis and the infiltration of CD163+ TAMs." (PMID 37876933, 2023). "A high density of CD163+ M2-macrophages is predominantly associated with poor prognosis in ovarian cancer and known to be involved in tumor invasion, angiogenesis, metastasis, and early recurrence." (PMID 37342190, 2023). "A meta-analysis showed that a high density of CD163+ TAMs infiltration was associated with poor prognosis in ovarian cancer." (PMID 35086548, 2022). "In vitro—Human monocyte cell-line THP-1-stimulated and ovarian cancer cell-lines (to produce tumor associated M2 macrophages cell-line (CD163 and CD209))." (PMID 36140188, 2022). "Of interest, CD163 expressing TAMs have been linked to poor prognosis, overall survival and metastasis of a range of malignancies, including colorectal and ovarian cancers." (PMID 33924378, 2021). "Some studies demonstrate high M2-like TAM (CD163+) levels in primary ovarian cancer tumors, and a high proportion of the CD163+/CD68+ TAM phenotype, is associated with poor PFS." (PMID 34677277, 2021). "Accordingly, studies have reported that high ratios of intra-tumoral CD8/Tregs or CD68/CD163 macrophages were associated with improved overall survival in ovarian cancer." (PMID 32852603, 2021). "In module C, CD163 had the most connections with other members of the module, which is reported to related to tumor associated macrophages and poor prognosis in ovarian cancer." (PMID 33987033, 2021). "Our results further revealed an association between higher CD80/CD163 ratio at the tumor IF and improved survival, similarly to what was reported in ovarian cancer." (PMID 31481956, 2019). "A number of studies have found an association between CD163 expression and ovarian cancer, notably in the expression of tumour-associated macrophages." (PMID 23339669, 2013). "Besides its multiple functions, such as immune modulation, high serum CD163 levels have been associated with poor survival outcomes in various malignancies, including ovarian cancer." (PMID 36669591, 2023). "This signature features known disease drivers and oncogenic ECM proteins associated with ovarian cancer progression and metastasis (e.g., NNMT, CD163, and FN1) and sheds light on proteins with high therapeutic potential." (PMID 41233595, 2026). "To determine if HMGCR expression in TAM is associated with poor prognosis and tumor progression, we checked the expression of HMGCR and CD163 in ovarian cancer patients." (PMID 40820860, 2025). "In ovarian cancer, CD163 plays a significant role in the tumor microenvironment, where it is upregulated on TAMs found in malignant ascites." (PMID 40330466, 2025). "shows that despite high CD163 expression, TAMs in ovarian cancer exhibit a mixed-polarization phenotype that includes features of both M1 (pro-inflammatory) and M2 macrophages." (PMID 40330466, 2025). "Consistent with our transcriptomic data, CD163+ macrophages were abundantly detected within metastatic sites in the omentum, strongly suggesting their critical role in promoting ovarian cancer dissemination and colonization." (PMID 41208978, 2025).
ovarian carcinoma (continued). "A previous study reported that CSF1 blockade in ovarian cancer models resulted in a significant reduction in CD163+ M2-like TAMs, with a concomitant increase in M1-polarized macrophages producing CXCL10, a chemokine crucial for T-cell recruitment." (PMID 40330466, 2025). "Prior studies identified a specific subset of omental resident macrophages, characterized by co-expression of Cd163 and Tim4, which establishes a favorable niche for ovarian cancer metastasis." (PMID 41208978, 2025). "To further validate the spatial localization and biological relevance of these macrophages in the context of ovarian cancer metastasis, we performed H&E staining and IHC for CD163 on mouse and human omental tissues bearing ovarian cancer metastases." (PMID 41208978, 2025). "The molecular mechanism of CD163+ TAM-derived exosome-induced cisplatin resistance in ovarian cancer ascites involves the transfer of exosomes containing miR-221-3p from TAMs to ovarian cancer cells." (PMID 40330466, 2025). "In a mouse model of ovarian cancer, CD163+Tim4+ resident macrophages residing in the omentum were shown to be responsible for the metastatic spread of cancer cells." (PMID 39516356, 2024). "A study focused on ovarian cancer, for instance, unveiled a significant increase in both CD68 + TAMs and CD163 + TAMs density in advanced ovarian cancer, with CD163 + TAM infiltration being associated with an adverse prognosis in ovarian cancer patients." (PMID 38273373, 2024). "The depletion of omental resident CD163+Tim4+ macrophages demonstrated that these cells play essential roles in tumor progression and the metastatic spread of disease in ovarian cancer." (PMID 39516356, 2024). "In a mouse model of ovarian cancer, a subset of tissue-resident macrophages (Tim4+CD163+) has been shown to play a key role in metastatic seeding at these sites." (PMID 39402303, 2024). "Tim‐4, CD16, CD206, CD163, and CRIg are some possible markers of resident macrophages in ascites of ovarian cancer patients." (PMID 39494816, 2024). "Tissue-resident omental macrophages, CD163+Tim4+, promote tumor growth and spread in preclinical ovarian cancer murine models." (PMID 38451784, 2024). "Thus, it has been suggested that molecules such as CD16, CD206, CD163, CRIg, and Tim-4 may be associated with resident macrophages in the human peritoneal fluid, and macrophages expressing these molecules are also found in ascites from ovarian cancer patients." (PMID 37180125, 2023). "Single-cell RNA seq of metastatic omental tumor of ovarian cancer identified a CD163+CD204+ cluster with high CD14 and CD16 expression and a NR1H2+ cluster in macrophages of all 6 cases." (PMID 37180125, 2023). "Another in vitro coculture study showed the heterogeneous ability of different ovarian cancer cell lines to increase CD163 expression in primary monocyte-derived macrophages." (PMID 37545408, 2023). "The RNAseq data from the UKE ovarian cancer patient cohort showed that the expression of CD163 was correlated with other M2 markers, such as CD206 and CD204, and was also positively associated with the expression of TIGIT and TIM-3." (PMID 37876933, 2023). "‐CD163+ Tim4+ macrophages promoted the acquisition of cancer stem cell and epithelial‐to‐mesenchymal transition characteristics by ovarian cancer cells." (PMID 36658699, 2023). "It has been shown that there are increased CD163+ TAMs in the malignant ascites of patients with ovarian cancer." (PMID 37545408, 2023). "They usually show an M2-like phenotype, and ovarian cancer TAMs are reported to express high levels of CD163 and CD206." (PMID 35842650, 2022). "In ovarian cancer, high level of POSTN in ovarian cancer ascites fluids correlates with CD163 + TAMs infiltration and poor relapse-free survival in patients." (PMID 36550569, 2022). "The survival and prognosis of ovarian cancer patients are strongly associated with TAMs, especially M2-like (CD14 + CD163 +) TAMs." (PMID 35842650, 2022).
ovarian carcinoma (continued). "In vivo mouse studies of ovarian cancer identified a subset of CD163+ Tim4+ resident macrophages with the omentum that were the primary drivers of metastasis." (PMID 35565348, 2022). "By PPI network and MCODE module, TYROBP, ITGB2, C1QB, C1QA, CD53 and CD163 have top connectivity among all DEGs and are considered to have important relationship to immune response in ovarian cancer." (PMID 33987033, 2021). "CD163 is a characteristic marker of M2 macrophages, which are the most predominantly TAM subtype found in ovarian cancer and are associated with tumor invasion, angiogenesis, metastatic disease, and early recurrence." (PMID 34060699, 2021). "Consistently, a unique subset of CD163+Tim-4+ resident omental macrophages was defined to be responsible for metastatic spread of ovarian cancer cells recently." (PMID 32300343, 2020). "CD163 and CD206 mRNA expression is also associated with IL-10 levels in ascites, which indicate a shorter relapse free survival (RFS) in patients with ovarian cancer." (PMID 32774171, 2020). "Further, some TAMs also express multi drug resistance protein 1 supporting chemoresistance as demonstrated on CD163+CD204+ TAMs in epithelial ovarian cancer." (PMID 32752088, 2020). "Using histological data obtained from 395 EOC patients, it was found that CD163+ TAM infiltration correlates with higher expression of ZEB1 that drives EMT in ovarian cancer cells." (PMID 33194645, 2020). "CD163, MS4A4A and MS4A6A are surface markers for M2 macrophages, and higher MS4A4A and MS4A6A levels were associated with a poorer prognosis in ovarian cancer patients." (PMID 33323552, 2020). "Several adverse clinical markers are highly expressed by ovarian cancer TAMs, including CD163, Procollagen C-endopeptidase enhancer 2 (PCOLCE2), IL-6 and IL-10." (PMID 32774171, 2020). "After 72 hours of co‐culture, the macrophage phenotype highly expressed M2 marker CD163 and lowly expressed M1 marker HLA‐DR, suggesting that the macrophages had already differentiated into M2 phenotypes after the co‐culture with ovarian cancer cells." (PMID 32329191, 2020). "In mouse model of ovarian cancer, CD163+ Tim4+ macrophages from omentum, which have embryonic origin and are uniquely independent of bone marrow-derived monocytes, contributed significantly to the metastatic spread." (PMID 33194645, 2020). "The only established prognostic markers for cells in ovarian cancer ascites are the surface expression of CD163 and CD206 in TAM (13, –15)." (PMID 29141914, 2018). "We therefore additionally grouped samples according to the expression of CD163, previously established as a TAM marker associated with a poor clinical outcome of ovarian cancer." (PMID 28327095, 2017). "Elevated soluble CD163 in serum is a potential biomarker for the diagnosis of myeloma and ovarian cancer." (PMID 29152078, 2017). "Previous studies aimed at characterizing TAMs in ovarian cancer demonstrated that they most closely resemble M2-polarized macrophages and express M2 markers such as CD163, CD204, CD206 (Mannose Receptor), and IL-10." (PMID 27462782, 2016). "Serum levels of CD163 have also been shown to predict poor prognosis in patients with ovarian cancer." (PMID 24936477, 2014). "There is a paucity of data on hCAP-18, lactoferrin and CD163 and their expression in circulating plasma, and in the tumours themselves, from women with ovarian cancer, specifically with differing grades of disease." (PMID 23339669, 2013). "The expression of ir CD163 was confined to stromal cells but was similarly increased in tissues obtained from women with ovarian cancer." (PMID 23339669, 2013). "Studies have revealed that a high density of CD163-positive M2 macrophages and a high CD163/CD68 ratio are significantly associated with worse progression-free survival (PFS) and overall survival (OS) in patients with advanced ovarian cancer." (PMID 40330466, 2025).
ovarian carcinoma (continued). "Interestingly, phagocytic/fusion cells with the epithelial marker EpCAM and the macrophage marker CD163 were only observed in blood cells from patients with ovarian cancer." (PMID 38356723, 2024). "Specific depletion of CD163+ TIM-4+ macrophages prevent metastasis of ovarian cancer." (PMID 38229178, 2024). "Similarly, high levels of POSTN in ascetic fluids of ovarian cancer patients correlated with high CD163+ TAM recruitment and with decreased relapse-free survival." (PMID 38942020, 2024). "Furthermore, the expression of CD163 and TIGIT was associated with unfavorable clinical parameters, indicating a prognostic relevance of M2 infiltration in ovarian cancer." (PMID 37876933, 2023). "However, direct analysis in patient samples with ovarian cancer has shown a complex picture with TAMs overexpressing both CD163 and CD86 markers compared with tumor-naïve macrophages." (PMID 37545408, 2023). "Depletion of CD163 + Tim4+ macrophages in a mouse model of orthotopic ovarian cancer demonstrated the critical role of these protumor TAMs in promoting the malignant progression of ovarian cancer." (PMID 37545408, 2023). "Compared with control exosomes, exosomes derived from ETS1-overexpressing ovarian cancer cells (LV-ETS1 Exos) stimulated the polarization of more macrophages toward the M2 phenotype (CD163 marker), as well as the production of more CXCL5 and CCL2 in macrophages, via integrin αvβ5/AKT/Sp1 signaling." (PMID 36477408, 2022). "Depletion of CD163 + macrophages can restrict omental metastasis of ovarian cancer." (PMID 36477408, 2022). "Also CD163+ TAMs have been found within milky spots and have been shown to promote metastasis of ovarian cancer cells to the omentum through increases in EMT and cancer stem cell markers." (PMID 35574025, 2022). "In the mouse model of metastatic ovarian cancer, tissue-resident CD163+, Tim4+ macrophages in the omentum (the fat deposit in the peritoneal cavity) contributed significantly to the metastatic spread of ovarian cancer cells and the development of invasive disease." (PMID 32752088, 2020). "Similarly, some smaller studies with mixed histological types, evaluating CD163 expressing macrophages in ovarian carcinoma, have been published." (PMID 31980961, 2020). "Moreover, CD163+Tim-4+ tissue-resident macrophages promoted the circulating stem cell-like phenotype of ovarian cancer cells." (PMID 32300343, 2020). "In addition, VSIG4 transcripts were highly correlated with the expression of the alternative macrophage marker CD163 in human ovarian cancer." (PMID 32780724, 2020). "Similarly to CD163, the M2 marker CD206 is associated with poor prognosis in TAMs from ovarian cancer." (PMID 31096567, 2019). "Analyses of CD163-immunostained tumor sections revealed increased M2 type tumor-associated macrophage infiltration in siPDLIM2-transfected OVCAR-3 and Caov-3 ovarian cancer cell specimens compared to control." (PMID 26593252, 2016). "Single cell studies also reveal the highest degree of CD8+ T-cell exhausted populations and CD163+ macrophages in ovarian cancer with an infiltrated immune phenotype, speculating that suppressive macrophages could contribute to lesion growth and progression to EAOC." (PMID 37569458, 2023). "Furthermore, a negative effect of CD163+ tumor-associated macrophages on survival was reported in a meta-analysis of patients with ovarian carcinoma." (PMID 31980961, 2020). "We have previously shown that TAM in ovarian cancer ascites can be stratified into subsets based on the expression of the surface markers CD163 and CD206 (encoded by the MRC1 gene), both of which show a high degree of variance among patients (1–94% CD163+ or CD206+ of the CD14+ TAM population)." (PMID 29141914, 2018).